DAPK1 (death associated protein kinase 1)
Diseases named in the same sentence as DAPK1 in open-access papers (continued):
Sharing a sentence is not in itself a finding about the gene and the disease.
gastric cancer (36 papers, 2002 to 2025). A primary or metastatic malignant neoplasm involving the stomach. "Further analysis of the clinicopathological features indicated that aberrant methylation of DAPK1 is positively associated with the tumorigenesis of gastrointestinal cancer, and metastasis of gastric cancer." (PMID 28934284, 2017). "DAPK1, a positive mediator of gamma-interferon induced programmed cell death, was reported to be fully hypo-methylated or up-regulated in several types of cancer, including fistula associated mucinous type anal adenocarcinoma, nasopharyngeal carcinoma and gastric cancer." (PMID 30778372, 2018). "Survival analysis showed that low expression of DAPK1 was a favorable prognostic factor of overall survival and disease-free survival for gastric cancer patients." (PMID 36290392, 2022). "The functions of DAPK1 in gastric cancer were determined by proliferation, migration and invasion assays." (PMID 36290392, 2022). "In this study, the TCGA and GEO datasets were used to explore the expression and role of DAPK1 in gastric cancer." (PMID 36290392, 2022). "Functional experiments demonstrated that DAPK1 can promote the migration and invasion of gastric cancer cells." (PMID 36290392, 2022). "Kaplan–Meier analysis showed that low expression of DAPK1 was a favorable prognostic factor of overall survival and disease-free survival for gastric cancer patients." (PMID 36290392, 2022). "The functional experiments demonstrated that DAPK1 can promote the migration and invasion of gastric cancer cells." (PMID 36290392, 2022). "In gastric cancer cells, both b-catenin and DAPK1 expression was regulated by S100P, which is an oncogenic factor in gastric cancer." (PMID 28740751, 2017). "Treatment with the HDAC inhibitor sodium butyrate increased the expression of caspase-3 and DAPK1/2 genes but decreased the expression of Bcl-2 in human gastric cancer cells." (PMID 22160140, 2012). "Our experiments demonstrate that sodium butyrate induced DAPK1/2 expression but down-regulated FAK expression in human gastric cancer cells." (PMID 22160140, 2012). "In contrast to s-DAPK-1, there is considerable evidence in the literature on microRNAs targeting DAPK-1; for example, DAPK-1 has been reported to be modulated by miR-26b-5p and miR-632 microRNAs in the contexts of intestinal ischemia and gastric cancer, respectively." (PMID 40699815, 2025). "Our previous study also discovered that high DAPK1 expression promotes gastric cancer metastasis." (PMID 40918124, 2025). "Death-associated protein kinase 1 (DAPK1) is a positive mediator of interferon-gamma-induced programmed cell death and is a tumour suppressor candidate that inhibits tumour immune evasion in gastric cancer." (PMID 37065474, 2023). "The expression of DAPK1 was significantly up-regulated in gastric cancer tissues." (PMID 36290392, 2022). "Methylation of DAPK1 is reported in other cancers like gastric cancer." (PMID 35421941, 2022). "In addition, genes co-expressed with DAPK1 in gastric cancer were estimated through the WGCNA and correlation analysis." (PMID 36290392, 2022). "In this study, we found that the expression of DAPK1 was up-regulated in gastric cancer tissues." (PMID 36290392, 2022). "That is, along with the process of gastric carcinogenesis, the methylation rate of DAPK1 gene will increase, so it can be speculated that DAPK1 can be used as a marker of gastric cancer." (PMID 34422899, 2021). "Moreover, hypermethylation of the DAPK1 promoter is reported in tumor tissues and lymph nodes of patients with gastric cancer and head and neck tumors." (PMID 33201837, 2020). "Conversely, the levels of the tumor suppressors (e.g., DAPK1, TIMP3, GRIN2B, SLC5A8, and CDH1) are low in the gastric tissues of patients with gastric cancer." (PMID 35211104, 2022). "Promoter methylation of RNF180, DAPK1 and SFRP2 can be detected in plasma DNA of patients with gastric cancer." (PMID 28418867, 2017).
gastric cancer (continued). "Analysis of the general expression patterns revealed that sodium butyrate increased the expression of DAPK1/2 but decreased the expression of FAK and induced changes in the proliferation of apoptosis-related genes in human gastric cancer cells." (PMID 22160140, 2012). "Expression of DAPK1/2 was increased, while that of FAK was decreased in human gastric cancer cells." (PMID 22160140, 2012). "Our results found that DAPK1/2, but not DAPK3, expression was increased by sodium butyrate treatment in human gastric cancer cells." (PMID 22160140, 2012).
Stroke (32 papers, 2013 to 2025). Sudden impairment of blood flow to a part of the brain due to occlusion or rupture of an artery to the brain. "For example, a study by Pei suggested that the loss of DAPK1 expression and the loss of the DAPK1 kinase domain can protect mice from neuronal and spinal cord injury, respectively, caused by stroke." (PMID 39833100, 2025). "In AD and stroke, DAPK1 is linked to apoptosis, and these findings show that DAPK1 alsoplays a protective role in TBI by inhibiting the apoptosis of neurons." (PMID 35783103, 2022). "Depletion of DAPK1 expression and deletion of the kinase domain of DAPK1 in mice protects against neuronal and spinal damage caused by stroke, respectively." (PMID 35742817, 2022). "In vivo and in vitro results demonstrated that levels of miR-124 were significantly decreased following stroke, whereas changes in death-associated protein kinase 1 (DAPK1) levels exhibited the converse pattern." (PMID 33841091, 2021). "DAPK1 plays a pivotal role in regulating various biological processes, including apoptosis and autophagy, and is implicated in pathogenesis of several disorders, such as cancer, stroke and brain damage, neurodegenerative and within their kinase domains." (PMID 40918124, 2025). "Similar to AD, TBI/CTE, and stroke/VaD, our group demonstrated a preE-associated Pin1 inactivation by cysteine-113 (Cys113) oxidation, and Ser71 phosphorylation by death associated protein kinase 1 (DAPK1), and concomitant induction and cytoplasmic sequestration of cis P-tau and protein aggregation." (PMID 39857613, 2024). "The substrates and molecular signaling pathways associated with DAPK1 in stroke damage are gradually being canvassed, but the mechanisms underpinning changes in DAPK1 levels remain unclear." (PMID 33841091, 2021). "Collectively, DAPK1 is a critical mediator of neuronal cell death in stroke, acting through multiple pathways to influence cell fate." (PMID 40918124, 2025). "During a stroke, DAPK1 is recruited to the NMDA receptor NR2B subunit, enhancing receptor activity and leading to excitotoxicity, a major cause of neuronal cell death." (PMID 40918124, 2025). "DAPK1 plays a significant role in the pathophysiology of stroke, primarily through its involvement in neuronal cell death pathways." (PMID 40918124, 2025). "Inhibition of DAPK1 activity has been shown to reduce neuronal cell death and improve outcomes in experimental models of stroke." (PMID 40918124, 2025). "Dysregulation of this pathway by DAPK1 can lead to increased neuronal apoptosis and cognitive dysfunction, particularly in post-stroke conditions." (PMID 40918124, 2025). "This section will provide an in-depth exploration of DAPK1’s involvement in different diseases, including cancer, stroke, neurodegenerative diseases, cardiovascular diseases, wound healing, kidney injury, and tuberous sclerosis complex." (PMID 40918124, 2025). "The extrasynaptic NMDARs containing GluN2B form a complex with death-associated protein kinase 1 (DAPK1) in ischemia and facilitates stroke damage." (PMID 39191395, 2024). "At extrasynaptic sites, the NMDA receptors, along with death-associated protein kinase 1 (DAPK1), contribute to stroke damage." (PMID 37927744, 2023). "Current research on DAPK1 mainly focuses on cancers, Alzheimer’s disease, stroke, Parkinson’s disease and epilepsy." (PMID 36338967, 2022). "Past studies have demonstrated the inhibition of TNF-α and IL-1β expression via modulation of DAPK1 signaling in stroke." (PMID 36016577, 2022). "Although miR-124 has various targets, the pathways involved in neuronal cell death are the most critical downstream players in stroke pathogenesis, and DAPK1 is a key protein involved in the cell death pathway." (PMID 33841091, 2021). "Western blot revealed that levels of DAPK1 protein were significantly higher in PIT-stroke mice than in sham mice and significantly higher in OGD neurons than in control neurons." (PMID 33841091, 2021).
Stroke (continued). "Our data revealed a significant increase in DAPK1 protein levels in the stroke brain and OGD neurons, and reduced miR-124 levels were observed." (PMID 33841091, 2021). "Overall, our study demonstrated the key role of the miR-124/DAPK1 pathway in neuronal survival in stroke." (PMID 33841091, 2021). "We observed similar changes in the levels of total and truncated DAPK1 forms in brain tissue samples obtained 2 h after reperfusion from a rat transient MCAO stroke model." (PMID 33265962, 2020). "Accordingly, numerous genetic and pharmacological DAPK1-targeting approaches have demonstrated neuroprotective and synapto-protective benefits in animal models of stroke, excitotoxicity, Alzheimer’s disease, Parkinson’s disease, and chronic stress." (PMID 33250715, 2020). "Over the past decades, several groups have made efforts to decipher DAPK1’s cellular function in stroke, focusing on its biochemical properties, regulation, and especially the target substrates in ischemic injuries." (PMID 27447806, 2017). "The purposes of this review are to provide a comprehensive overview of the recent literatures on DAPK1 signals in ischemic stroke and to help us better understand the molecular mechanisms of neuronal cell death during stroke injuries." (PMID 27447806, 2017). "In addition, DAPK1, which is abundantly expressed in the brain, has been linked to neurological diseases associated with neuronal injury and may serve as a target for therapeutic intervention in the treatment of stroke, epilepsy, and Alzheimer’s disease." (PMID 27447806, 2017). "We hope to provide exhaustive summaries of relevant studies on DAPK1 signals involved in stroke damage." (PMID 27447806, 2017). "Next, we identified small-molecule compounds that inhibit DAPK1 and are thus potential leads for the development of compounds with neuroprotective properties and potential application for the treatment of stroke." (PMID 25382253, 2015). "In a rat stroke model, DAPK1 combines with NMDA receptors leading to NMDA receptors phosphorylation and over-activation." (PMID 24755839, 2014). "It is found that after stroke injury, NMDAR interacts with Death Associated Protein Kinase 1 (DAPK1) through NR2B subunit, a member of a serine/threonine kinase family well known for their roles in cell death." (PMID 25984336, 2014). "Stroke injury activates DAPK1, which migrates to extrasynaptic site and binds to NR2B receptor subunit." (PMID 25984336, 2014). "Therapeutically, targeting DAPK1 presents a promising strategy for neuroprotection in stroke." (PMID 40918124, 2025). "In the setting of ischemic stroke, DAPK1-mediated autophagy may contribute to cell death, further highlighting its complex role in stroke pathology." (PMID 40918124, 2025). "Since DAPK1 is also dysregulated in various brain disorders such as stroke and AD, and because DAPK1 and SENP1 directly bind, we wondered whether DAPK1 can affect SENP1 function." (PMID 41272902, 2025). "It has been reported that DAPK1 phosphorylates NR2B in stroke." (PMID 35783103, 2022). "The interaction between NR2B and DAPK1 in stroke has been reported." (PMID 35783103, 2022). "It has been shown that DAPK1 activation triggers aberrant tau phosphorylation in AD and stroke 12, 16, while whether DAPK1 and Pin1 also participate in Aβ species-induced tau dysregulation remains to be determined." (PMID 35002518, 2022). "An increase in miR-124 via downregulation of DAPK1 rescued stroke damage in mice." (PMID 33841091, 2021). "Furthermore, down-regulation of miR-124 induced upregulation of DAPK1 protein levels, thereby inducing neuronal death and stroke damage." (PMID 33841091, 2021). "Inhibition of DAPK1 activity confers neuroprotective effects in stroke model mice." (PMID 33841091, 2021).
Stroke (continued). "Among them, DAPK1 is known to interact with the excitotoxicity driver NMDA receptor (NMDAR), and in sudden pathophysiological conditions of the brain, e.g., stroke, several lines of evidence link DAPK1 with the transduction of glutamate-induced events that determine neuronal fate." (PMID 33265962, 2020). "Approaches to reduce DAPK1 activity have demonstrated benefit in animal models of stroke, Alzheimer’s disease, Parkinson’s disease, and chronic stress, indicating that DAPK1 may be a novel target for neuroprotection." (PMID 33250715, 2020). "Ca2+-dependent kinases could also include those that phosphorylate NMDA receptor NR2B subunits, e.g., DAPK1, which is known to play a role in stroke." (PMID 33490083, 2020). "Consistent with the role of DAPK1 in amplifying exGluN2B function in ischemia, genetic manipulations eliminating DAPK1 expression or kinase activity promote neuroprotection and synaptic preservation in models of stroke, excitotoxicity, and Alzheimer disease." (PMID 33250715, 2020). "To delineate specific and differential neuronal DAPK1 interactors in stroke-like conditions in vitro, we exposed primary cultures of rat cortical neurons to oxygen/glucose deprivation (OGD), a condition that increases reactive oxygen species (ROS) and lipid peroxides." (PMID 33265962, 2020). "However, the genetic deletion of the DAPK1 kinase domain in mice protects against spine damage and improves neurological functions against stroke insults." (PMID 31248062, 2019). "Interestingly, DAPK1 interacts with tau and directly phosphorylates tau at Ser262 in the cortical neurons of a mouse model of stroke induced by MCAO." (PMID 31248062, 2019). "Thus, targeting DAPK1-NMDA receptor interaction can be considered as a practical strategy for stroke therapy." (PMID 27447806, 2017). "In this review, we focus on the role of DAPK1 in neuronal cell death after stroke." (PMID 27447806, 2017). "Death-associated protein kinase 1 (DAPK1) has been associated with N-methyl-d-aspartate (NMDA) receptor-mediated excitotoxicity, and has recently been suggested as a target for the treatment of stroke." (PMID 25382253, 2015). "Emerging evidence suggests that inhibition of death-associated protein kinase 1 (DAPk1), which prevents excessive NMDA receptor (NMDAR) activation without interfering with physiological functions, provides neuroprotection in animal models of adult stroke." (PMID 23880846, 2013). "Interestingly, inhibition of DAPK1 activity or expression attenuates neuronal cell death in a stroke mouse model and AD-related neuropathology in AD animal models, suggesting that inhibiting DAPK1 might protect neurons from neuronal damage 22-28." (PMID 34239362, 2021). "We next assessed whether levels of DAPK1, a downstream gene of miR-124, were altered post-stroke." (PMID 33841091, 2021). "In addition, PNS acted on death-associated protein kinase 1 (DAPK1) to inhibit Ser-1303 phosphorylation in an Anti-N-methyl-d-aspartate receptor (NMDAR), blocking the overactivation of NMDAR against excitotoxicity induced by stroke." (PMID 34658860, 2021). "Hence, changes in the miR-124 target, DAPK1, post-stroke were investigated in this study." (PMID 33841091, 2021). "Therefore, disrupting DAPK1-relevant cell death pathway could be considered as a promising therapeutic approach in stroke." (PMID 27447806, 2017). "Thus, drugs that enhance the inhibitory activity of DANGER on the DAPK1 signaling pathway might be useful in blocking cell death in stroke and neurodegenerative diseases." (PMID 27447806, 2017).
Stroke (continued). "DAPK1 is of particular interest in stroke to us because of a quantitative proteomic analysis of the death-signaling proteins that are enrolled to the cytoplasmic tail of the N-methyl-D-aspartate receptor (NMDAR) during cerebral ischemia revealing DAPK1 as the most prevalent protein." (PMID 27447806, 2017). "By defining the exact binding domain of DAPK1 in NR2B, an interference peptide (NR2BCT) was designed to effectively disrupt the interaction of DAPK1 with NMDARs during stroke." (PMID 25984336, 2014). "Furthermore, the development of specific DAPK1 inhibitors that disrupt its interaction with the NMDA receptor NR2B subunit is an area of active research, with potential implications for reducing stroke-induced neuronal cell damage." (PMID 40918124, 2025). "Despite the growing role of DAPK1 as an intracellular hub kinase, the mediators through which NR2B-DAPK1 complex leads towards neuronal death in stroke remain unclear." (PMID 33265962, 2020). "The administration of a peptide NR2BCT1292–1304 to uncouple of the activated DAPK1 from the NMDA receptor complex protects against brain damage in stroke without affecting the physiological actions of the NMDA receptors." (PMID 27447806, 2017). "It was shown that DAPk1 physically and functionally interacts specifically with the NMDA receptor NR2B subunit at extra-synaptic sites, which has been identified as a central interaction site that mediates stroke damage." (PMID 23880846, 2013). "Thus inhibition of DAPk1 prevents the over-stimulation of NMDARs following stroke damage, without interfering with its physiological functions." (PMID 23880846, 2013). "Thus, the inhibition of DAPK1 does not interfere with physiological function and prevents the excessive stimulation of NMDA receptors following stroke injury." (PMID 31248062, 2019).